IL6 (interleukin 6)
Diseases named in the same sentence as IL6 in open-access papers (continued):
Sharing a sentence is not in itself a finding about the gene and the disease.
tumor (continued). "Paracrine IL-6 signaling from tumor-infiltrating inflammatory cells is more important because these cells have a greater inflammatory cytokine secretion capacity, including IL-6." (PMID 24021059, 2013). "Mutations within tumors can play a role in this process; BRAF mutations drive tumor cells to produce pro-inflammatory cytokines like VEGF, IL-10, and IL-6, while at the same time decreasing expression of anti-tumor cytokines such as IL-12." (PMID 24829749, 2013). "By viable cell counting over 6 days and observation of xenograft tumors, the IL-6 silencing vector significantly inhibited tumor growth in vitro and in vivo." (PMID 23561329, 2013). "In summary, gastric stromal fibroblasts produced IL-6 in response to stimulation from tumor cells through IL-1 signaling in gastric tumorigenesis, and that secreted IL-6 promotes tumor growth through STAT3 activation." (PMID 23593346, 2013). "Consistent with our findings, previous paper indicated that IL-17 induces IL-6 production by tumor cells and stromal cells, which in turn activated Stat3." (PMID 24453427, 2013). "IL-6 has had tumor-promoting effects on both malignant and stromal cells in a range of experimental cancer models." (PMID 24202339, 2013). "The HCMV protein US28 is a constitutively active chemokine receptor homologue that induces COX-2 expression and results in STAT3 phosphorylation, which increases the production of VEGF and IL-6 and consequently induce tumor formation in vivo." (PMID 23451089, 2013). "Nonetheless, even with fewer immune cells, the tumor that originated from the DABK-stimulated cells had higher levels of IL-6 and IFN-γ mRNA, which are pro-inflammatory cytokines known to be important in the anti-tumor immune response." (PMID 23691222, 2013). "HCMV US2.8 is a chemokine receptor homologue that induces COX-2 expression, VEGF production, STAT3 phosphorylation and IL-6 production, all of which are relevant in tumor biology." (PMID 23451089, 2013). "In summary, metastasizing, but not non-metastasizing, tumor-derived factors induced MDSCs to produce more IL-6, and full activation of recruited MDSCs occurred in the primary tumor site and metastatic organs in the vicinity of metastasizing cancer cells." (PMID 24021059, 2013). "IL-6 is a known pro-inflammatory cytokine with an established role in tumor progression and metastasis." (PMID 23936495, 2013). "IL-6 has been reported to be indispensable for oncogene-induced cell transformation and tumorigenesis, indicating the importance of IL-6 in tumor initiation." (PMID 23593346, 2013). "In vivo, fibroblasts in tumor tissue have been postulated to serve as a source of pro-oncogenic cytokines, including IL-6." (PMID 24380387, 2013). "Interleukin-6 (IL-6) is a pleiotropic cytokine that affects various functions, including tumor development." (PMID 23593346, 2013). "Recently, phosphorylated-Stat3 expression in the tumor stroma, an indication of IL-6-JAK pathway activation, was thought to be a critical contributor to cancer progression and response to therapy by modulating PI3K pathway." (PMID 23922669, 2013). "In summary, this study establishes secretion of IL-6 by tumors cells following HY-PDT as a potential contributor of immune-stimulatory effects of apoptosis in tumor suppression." (PMID 23807226, 2013). "HNSCC tumors get nourished due to its microenvironment and are well supplied with soluble epidermal growth factor receptor (EGFR) and cytokine (IL-6), which play a critical role in tumor aggressiveness and their response to various therapies." (PMID 23414419, 2013). "Recent evidence has demonstrated that aberrant Stat3 signaling by Interlukin-6 (IL-6) in cancer cells is a major mechanism for tumor initiation, development, progression, and metastasis." (PMID 24191246, 2013). "Stromal-derived IL-6 promotes osteoclast activation, the formation of osteolytic bone metastasis, and the resistance of tumor cells to cytotoxic drugs." (PMID 24204677, 2013).
tumor (continued). "An orthotopic tumor implantation technique was used to examine the effects of the IL-6 silencing vector on invasive capability in vivo." (PMID 23637926, 2013). "Tumor-derived IL-6 drives STAT3 nuclear translocation in immature myeloid cells, thus promoting proliferation and inhibiting apoptosis of MDSCs." (PMID 24339824, 2013). "TNF, IFNγ, IL-6 and IL-11 gene expression were higher in non-tumor tissue from Iron/DSS and Control/DSS mice compared with colonic tissue from Iron and Control mice at day 78 (data not shown)." (PMID 24223168, 2013). "In our further study, wild-type mice were challenged with B16 tumor cells, followed by treatment of IL-6-neutralizing antibody or control rat IgG." (PMID 24453427, 2013). "IL-6 promotes the differentiation of Th17 cells, and IL-17A also amplifies IL-6 production in the tumor." (PMID 23372655, 2013). "TGF-β1 has been demonstrated to suppress INF-γ production by CD8+ T cells and to promote, in concert with IL-6, IL-1β, and IL-10, Treg generation, and Th17 differentiation, thus favoring tumor growth and progression." (PMID 23533994, 2013). "Interleukin-6 (IL-6) is a pleiotropic cytokine involved in tumor initiation, promotion, and progression." (PMID 23593346, 2013). "To extend our findings in vivo, we examined senescence (SA-β-Gal staining), DNA damage (53BP1), NF-κB activity (IκB-α) and the SASP (IL-6) in an Hs294T xenograft tumour after MLN 8237 treatment." (PMID 23180582, 2013). "Both GDNF and IL6 stimulate migration of breast cancer cell lines and in vivo inhibition of Ret significantly decreases tumour outgrowth and the metastatic potential of an ER+ model." (PMID 23868506, 2013). "In particular, Jagged1, which is a downstream mediator of the prometastatic TGF-β, promotes tumor growth through stimulation of IL-6 production from OBs, and directly it activates OC differentiation." (PMID 23710201, 2013). "A network of paracrine tumor-secreted factors, e.g., cytokine (Il-6) and chemokine (IL-8), contribute to tumor progression as attractants at the primary site." (PMID 25562519, 2013). "Our results indicated a potential role for IL-6, and IL-10 as a tumor marker for HCC with respect to AFP and this was in agreement with the previous studies." (PMID 27335826, 2013). "Here, we analyzed the effect of curcumin on the production of IL-6 in total tumor cell lysates, in MDSC of primary tumors and blood, and in serum of the 4T1 model." (PMID 24156030, 2013). "We assume that circulating IL-6 plays an important role to stimulate tumor growth in vivo, besides direct action on malignant cells." (PMID 23561329, 2013). "Inhibition of IL-6 signaling has been shown to attenuate tumor growth and the apoptotic and metastatic events in ovarian cancer patients." (PMID 23593315, 2013). "Our experiments have clearly shown that HY-PDT leads to increased release of IL-6 in the tumor microenvironment." (PMID 23807226, 2013). "Here, we observed that single-dose minocycline treatment resulted in considerable decrease in plasma and tumor IL-6 levels after both 4 and 24 h." (PMID 23593315, 2013). "One report using B16 melanoma cell lines showed that IL-17A promoted tumor growth via angiogenesis and induced IL-6 production, which in turn activated oncogenic Stat-3, up-regulating prosurvival and proangiogenic genes." (PMID 23372655, 2013). "There are many cytokines secreted by aHSCs that are associated with tumor invasion and metastasis, ingcluding HGF, EGF, IL-1, IL-2, IL-6, MMP-2, MMP-9, TGF-β, TNF-α, VEGF and Wnt families." (PMID 23622143, 2013). "Our data is consistent with a previous report concluding that monocytes purified from patients’ peripheral blood secrete increased levels of IL-6 upon stimulation with tumor-derived EVs." (PMID 23936495, 2013).
tumor (continued). "In the present study, we performed cell-culture and immunocompetent animal experiments to determine the correlation between IL-6 and the biological consequences following irradiation including tumor regrowth, angiogenesis and MDSC recruitment." (PMID 23806095, 2013). "With curcumin before tumor development in the combination therapy, the production of IL-6 was significantly decreased and IL-12 increased by myeloid-derived suppressor cells (MDSC), in correlation with improved CD4 and CD8 T-cell responses in blood." (PMID 24156030, 2013). "Another essential chemokine IL-6 produced by tumor cells and MSCs inhibit apoptosis by upregulating the expression of Bcl-xl." (PMID 23336752, 2013). "NF-κB activation is a result of underlying inflammation or a consequence of the formation of an inflammatory microenvironment during malignant progression characterized by up-regulation of the tumor promoting cytokines IL-6 and TNF-α." (PMID 24062985, 2013). "The second theory has also been supported by several authors who recently demonstrated that tumor cells can express IL-6 and even CRP." (PMID 23642165, 2013). "Conversely, tumor derived from mock-IL6-knockdown T24-GFPsi cells was approximately 10% of the average size of tumors derived from the IL6-knockdown T24-IL6si cells after 12 weeks of growth." (PMID 23762858, 2013). "CRH expression in the hypothalamic PVN was significantly lower in metastatic B16-F10-bearing mice than in non-tumor-bearing controls, whereas serum IL-6 increased." (PMID 23517603, 2013). "Here, we demonstrate that curcumin significantly reduced the production of IL-6 in vivo in the primary tumors (tumor cell lysates), and in MDSC of blood and primary tumors." (PMID 24156030, 2013). "They found MSCs-induced IL-6 secretion to be critical for the enhanced proliferation observed in Skov-3/MSC tumor growth assay." (PMID 23369187, 2013). "Here, we used fibroblasts isolated from primary human NPC tumor biopsy to develop an in vitro system to mimic the in vivo secretion of IL-6 by stromal cells and the subsequent activation of STAT3 in cancer cells." (PMID 24380387, 2013). "ROS, MMP-2 and interleukin-6 (IL-6) can interact directly between tumour cell spheroids and endothelial cell monolayer." (PMID 23516489, 2013). "From these experiments, we provide novel information regarding potential tumor-MDSC synergistic axis involving IL-6 and soluble IL-6Rα." (PMID 24021059, 2013). "The IL-6/CCL5 axis is thus another feed-forward cytokine loop between tumor and bystander cells in WM." (PMID 24106612, 2013). "IL-6 was increased between 5 and 64 fold in all H. pylori infected samples and 22 of 24 tumor samples up to 39 fold." (PMID 23365642, 2013). "Interferon-gamma (IFN-gamma) and interleukin-6 (IL-6) are multifunctional cytokines that regulate immune responses, cell proliferation, and tumour development and progression, which frequently have functionally opposing roles." (PMID 23384097, 2013). "At 28 weeks post-infection, in comparison with KrasG12D mice, more lesions were observed in KrasG12D; IL-6-/- mice with the majority of lesions in early stages of tumor development." (PMID 24260500, 2013). "Specifically, insulin-like growth factor 1 (IGF-1), transforming growth factor beta (TGF-β), and interleukin 6 (IL-6) secreted by astrocytes have been shown to promote proliferation of tumor cells in the brain." (PMID 24133630, 2013). "CCL2 is known to be a potent chemoattractant for MDSCs, and IL-6 has an impact on survival and proliferation of MDSCs in tumor microenvironment." (PMID 23372655, 2013).
tumor (continued). "Heterogeneous cell types that constitute the tumor microenvironment secrete the pro-inflammatory cytokines such as IL-6 or IL-8 that increase tumorigenic potential and promote therapeutic-resistance." (PMID 23390614, 2013). "As IL-6 was raised in the sample taken during the event and subsided thereafter coinciding with relief of symptoms, it can be proposed that the primary tumour released factors responsible for clinical findings." (PMID 23984107, 2013). "In this study, we showed that metastasizing cancer cells induced higher MDSCs infiltration and prompted them to secret exaggerated IL-6 as well as soluble IL-6Rα, which, in turn, triggered a persistent increase of pSTAT3 in tumor cells." (PMID 24021059, 2013). "To investigate the role of IL-6 trans-signaling in in vivo metastasis, we administered gp130-Fc to the tumor-bearing mice." (PMID 24021059, 2013). "Interleukin (IL)-6 is a pro-inflammatory cytokine that plays an active role in neoplasia, bone metabolism and iron homeostasis." (PMID 24204677, 2013). "IL-6 is a pleiotropic cytokine which is secreted by a wide variety of cell types, including lymphocytes, monocytes and tumor cells." (PMID 23599759, 2013). "In particular, IL-6 produced by tumor and/or activated immune cells has been postulated to be a key functional cytokine that alters tumor cells behaviors through complex mechanisms." (PMID 23593315, 2013). "TAM derive from circulating monocytes that differentiate locally into M2 in response to tumor microenvironmental factors, such as M-CSF and IL-6." (PMID 23409120, 2013). "Data coming from in vitro studies supports the pleiotropic (having both tumor promoting and tumor-counteracting effects) nature of interleukin-6 in breast tissue." (PMID 23762340, 2013). "From a panel of tumor-associated suppressive factors (including PGE2), we found only IL-6 and IL-10 to induce STAT3 phosphorylation during human MoDC development." (PMID 24324467, 2013). "STAT3, activated by pro-inflammatory cytokines like IL-6 from tumor-infiltrating myeloid cells, promotes both survival and growth of transformed intestinal epithelial cells." (PMID 23940556, 2013). "Selective Jak1 and Jak2 inhibitors can also inhibit Il-6/Stat3 signaling and concomitantly reduce tumor growth in xenograft models." (PMID 23520493, 2013). "After exposure to MF for 30 days, levels of IL-6 and G-CSF in tumor+MF group were reverted to those in control group." (PMID 24278103, 2013). "The tumor secreted factors such as IL6, IL10, and VEGF are responsible for this partial differentiation of dendritic cells, hence reducing their antigen presenting ability." (PMID 24199193, 2013). "Correlations among IL-6 levels, tumor regrowth, angiogenesis and myeloid-derived suppressor cell (MDSC) recruitment were examined in an animal model." (PMID 23806095, 2013). "Innate immune cells such as macrophages and dendritic cells cohabit the tumor stroma and are thought to play important roles in tumor progression via secretion of pro-inflammatory cytokines such as IL-1, IL-6, TNF-α and others." (PMID 22529912, 2012). "Both IL-6 and IL-12 are known to help tumor cells resist cytotoxic T lymphocytes and natural killer cells, leading to evasion from immune surveillance." (PMID 22815694, 2012). "Tumor-expressed IL6 had prognostic role in male OSCC patients as defined by the log-rank test (P = 0.014), but not in female patients (P = 0.959)." (PMID 23185547, 2012). "ELISA measurement of tumor and serum levels of proinflammatory cytokines, IL-6 and MCP-1, was performed." (PMID 22481916, 2012). "Chemotherapeutics such as doxorubicin and cisplatin have been shown to increase the secretion of cytokines such as IL-6 and IL-8, as well as other molecules from tumor cells." (PMID 22396773, 2012). "At first, we performed immunohistochemistry to detect IL-6 and evaluated the inhibitory effect of hochuekkito on IL-6 production in tumor-bearing mice." (PMID 23326296, 2012).
tumor (continued). "Hyper-IL-6 was actively secreted into the blood circulation as indicated by the same detection pattern over infection time in both the tumor and the blood." (PMID 22236378, 2012). "NF-κB activation in inflammatory cells controls the production of pro-inflammatory cytokines, including TNFα, IL-1, IL-6, and IL-23, which mediate tumor promotion and progression, as well as NF-κB activation in tumor cells." (PMID 23284890, 2012). "The changes of Th17 cells along disease progression were accompanied by alterations of IL-1β, IL-6, IL-17A, IL-23 in serum and IL-1β, IL-6 in tumor tissues." (PMID 22994684, 2012). "One mechanism for this rejection is related to interleukin (IL)-6 produced by tumor-infiltrating lymphocytes (TIL) that counteract the activities of TGF-β." (PMID 23136963, 2012). "These factors include proinflammatory cytokines such as TNF-α, IL-1β, and IL-6 and factors produced by tumour cells, each of which can be derived from the tumour itself and also from the host tissues." (PMID 22629149, 2012). "IMiDs can decrease the expression of the angiogenic factors VEGF and IL-6 leading to a reduction of growth and survival of tumor cells." (PMID 22761620, 2012). "Elevated levels of IL-6, an autocrine tumor growth factor produced by RCC cells, correlated with a poor outcome in patients with metastatic RCC." (PMID 22139406, 2012). "It inhibits the production of proinflammatory cytokines (TNF-α, IL-1, IL-6, and IL-12) and enhances that of anti-inflammatory cytokine (IL-10) resulting in an increase of the tumor-cell apoptosis." (PMID 22761620, 2012). "Oldford and coworkers demonstrated that Pam3CSK4 inhibited tumor growth in a mast cell and mast cell-derived IL-6-dependent manner." (PMID 22815882, 2012). "For analysis of oncolytic effects in live animals, DU-145 tumor-bearing mice were injected i.v. with either PBS or 5 × 106 pfu of GLV-1h68 and the hyper-IL-6-encoding GLV-1h90, respectively." (PMID 22236378, 2012). "IL-1β and TGF-β did not increase the CXCL7 expression in comparison with CTVT cells alone while IL-6 significantly down-regulated the expression of CXCL7 in tumor cells." (PMID 23136963, 2012). "The gene signatures presented herein derived from the tumor-osteoblast co-culture might become promising predictors of the response to therapies for bone metastasis and could provide valuable hints about the role of IL-6 and its associated genes in bone metastasis formation." (PMID 22235336, 2012). "We confirmed that the serum level of IL-6 was below the lower limit of detection in healthy control mice, and IL-6 level was significantly upregulated in untreated tumor-bearing mice." (PMID 23326296, 2012). "In human glioblastomas, pro-inflammatory cytokines, interleukin (IL)-1, IL-6 and IL-8, are expressed and secreted at high levels, and their expression levels are correlated with the histological grade of the neoplasms." (PMID 22330721, 2012). "The role played by IL-6 signalling in mediating tumour growth is equivocal, in certain tumour cells, it inhibits proliferation, whereas, in “in vivo” models, it stimulates cell growth." (PMID 22619672, 2012). "We used TLR4 ligand LPS, TLR3 ligand polyI:C and the Jonuleit cytokine cocktail most commonly used in today’s DC-based tumor vaccines consisting of IL-1β, IL-6, TNF-α and PGE2 for the generation of immunogenic DC." (PMID 23185370, 2012). "Secretion is crucial since the presence of hyper-IL-6 in blood is needed for the designer-cytokine to act outside the tumor tissue such as on megakaryocytes in the bone marrow or on skin keratinocytes." (PMID 22236378, 2012). "IL6 is an immunoregulatory cytokine and has been reported to promote tumor progression in human cancers." (PMID 23185547, 2012). "We see that TLR4/MyD88 regulates the expression of IL-6, which shows its important role in many aspects of tumour growth." (PMID 22533866, 2012). "Some studies show the role of IL-6 in tumor cells growth in vitro, but its exact role is still unclear." (PMID 23145063, 2012).